LINC00836 (long independently transcribed non-coding RNA 836)
Gene: Long non-coding RNA gene on chromosome 10 (25,651,712 to 25,732,935, forward strand). Ensembl gene ENSG00000280809.
Diseases named in the same sentence as LINC00836 in open-access papers:
LINC00836 is named in the same sentence as 3 diseases in open-access papers, as found by Europe PMC text mining. Sharing a sentence is not in itself a finding about the gene and the disease. The quoted sentences say what the papers report.
astrocytomas (1 paper, 2022). "No reports have documented the underexpression of LINC00836 in GBM compared with astrocytomas." (PMID 35456975, 2022).
glioma (1 paper, 2022). A benign or malignant brain and spinal cord tumor that arises from glial cells (astrocytes, oligodendrocytes, ependymal cells). "No published evidence was available as to the roles of the remaining eight underexpressed gene signatures (CHST9, CSDC2, ENHO, FERMT1, IGFN1, LINC00836, MGAT4C and SHANK2) regarding glioma pathogenesis or prognosis." (PMID 35456975, 2022).
LINC00836 also shares sentences with these, for which no sentence is quoted: Alzheimer disease (1 paper).